MPO (myeloperoxidase)
Diseases named in the same sentence as MPO in open-access papers (continued):
Sharing a sentence is not in itself a finding about the gene and the disease.
pancreatitis (continued). "Both plasma amylase and MPO levels in pancreas and lung significantly increased at 24 h after induction of pancreatitis compared to levels in normal animals." (PMID 23029434, 2012). "Pancreatitis also induced significant increases in MPO activity in both epididymal and mesenteric adipose tissue." (PMID 22870264, 2012). "Myeloperoxidase activity, which is accepted as an indicator of neutrophil infiltration, was significantly higher in the pancreatic tissue of the pancreatitis group treated with vehicle (p<0.01) than that of the control group." (PMID 27956946, 2009). "On the other hand, proanthocyanidin treatment in the pancreatitis group significantly decreased pancreatic MPO level (p<0.05) back to the levels of the control group." (PMID 27956946, 2009). "Therefore, MPO activity in those tissues, which is a standard measurement of neutrophil infiltration, has been used as a biochemical marker of pancreatitis." (PMID 34383255, 2021). "Since neutrophils-derived reactive oxygen species (ROS) are attributed to induce pancreatitis, the extent of neutrophil infiltration was evaluated by the means of the immunological staining of the pancreatic sections for MPO, which is general marker of neutrophil." (PMID 29847178, 2018). "In addition, the induction of pancreatitis significantly increased MPO activity in the lung tissue compared with the saline group." (PMID 29861777, 2018). "Myeloperoxidase is a classical biomarker of neutrophil activation and inflammation in pancreatitis." (PMID 29163548, 2017). "Administration of high doses of L-arginine, which is used as a relatively easy and reproducible model of pancreatitis, leads to significantly increased plasma amylase, pancreatic MPO activity, trypsin activation, and histological changes resembling acute pancreatitis in humans." (PMID 23613780, 2013). "However within the SPRC treated groups, mice injected with SPRC 3 h before the induction of pancreatitis showed significant reduction in MPO activity as compared to vehicle treated mice." (PMID 22396778, 2012). "Lung MPO levels, as an indicator of neutrophil activity, confirmed the significant neutrophil infiltration in the lungs from 9 h, with a peak activity noted at 24 h after pancreatitis induction." (PMID 23110041, 2012). "However, mice treated with SPRC 3 h before the induction of pancreatitis had significant reduction in cellular infiltration as evidenced by decreased lung MPO activity (SPRC 3 h+Cae) and histology (SPRC 3 h+Cae)." (PMID 22396778, 2012). "Moreover, the Hsp72 overexpression did not affect the development of pancreatitis-associated lung injury as determined by histological analysis and measurement of myeloperoxidase levels, which represents an enzyme found in the infiltrating neutrophils." (PMID 22792201, 2012). "Compared to DMSO‐treated pancreatitis mice, the injection of AT7519 significantly induced the levels of pancreatic enzymes in the pancreatic tissues, including trypsin and MPO as well as the levels of lipase in the serum." (PMID 35634959, 2022). "Capsazepine caused a downregulation of various inflammatory parameters such as myeloperoxidase (MPO) activity, pancreatic edema, and histological damage in leukotriene B4 (LTB4)-induced pancreatitis." (PMID 30871017, 2019). "When sections were stained with an antibody against myeloperoxidase (MPO), the density of MPO+ cells in pancreatitis was 1.9- and 1.6-folds higher than wt BMC and no BMC injection groups, separately (p ≤ 0.02 for both)." (PMID 34485535, 2021). "None of the parameters of pancreatitis, including edema, amylase, MPO, and histological scoring was elevated in Piezo1aci KO mice treated with Yoda1." (PMID 29712913, 2018). "Results showed that pancreatic injury, as evidenced by plasma amylase, pancreatic MPO and histology, and pulmonary injury, as evidenced by lung MPO and histology were significantly ameliorated in the mice treated with SPRC 3 h prior to the induction of pancreatitis." (PMID 24278674, 2012).
pancreatitis (continued). "Hamsters induced by L-arginine and Na-taurocholate had significantly increased pancreatic MPO activity respectively, but the changes in MPO activity did not reveal the neutrophil infiltration in caerulein- and ethanol + POA-induced pancreatitis." (PMID 27302647, 2016).
depression (40 papers, 2013 to 2025). "Previous studies on the relationship between MPO and psychiatric disorders have primarily focused on its association with depression." (PMID 40401059, 2025). "This study did not only reveal the impact of MPO as a potential biomarker of depression caused by an AMI." (PMID 36358455, 2022). "MPO is a potential biomarker for AMI-induced depression, indicating a depression-associated suppression of the innate immune system." (PMID 36358455, 2022). "In a small case-control study of recurrent depressive disorder, MPO expression associates with measures of cognitive function including executive function (Trail making test, Stroop test), verbal fluency, and auditory-verbal learning." (PMID 36083988, 2022). "C-reactive protein (CRP), interleukin–6 (IL–6), and tumor necrosis factor alpha (TNF-α) have previously been shown to associate with LUTS, depression and anxiety, while myeloperoxidase (MPO) has also been linked to the development of depression." (PMID 26445118, 2015). "Notably, MPO inhibition has been proposed as a potential therapeutic strategy for treating inflammation-associated major depressive disorder." (PMID 40401059, 2025). "In this study, MPO was significantly associated with AMI-induced depression." (PMID 36358455, 2022). "Indeed, lower levels of MPO are linked with reduced cardiovascular diseases, cytokine production, and inflammation that usually coexist with depression." (PMID 35203908, 2022). "Thus, MPO might be a suitable biomarker for AMI-induced depression, indicating a depression-associated suppression of the innate immune system." (PMID 36358455, 2022). "MPO has been defined as a marker of immune activation for major depression, and higher MPO levels were reported in depressed bipolar patients." (PMID 41300145, 2025). "Compared to control groups, patients with depression exhibit significantly elevated MPO expression at both the mRNA and protein levels, highlighting its crucial role in cognitive function regulation." (PMID 40401059, 2025). "Another study found that the impact of acute COVID-19 on affective symptoms in long-COVID (anxiety and depression) were partially mediated by reduced GPx activity, lower zinc levels, and increased myeloperoxidase and nitric oxide production." (PMID 40429727, 2025). "A low baseline MPO level was a significant predictor of depression development after MI at 6 months, in contrast to the excessive immune inflammation that is commonly observed." (PMID 41301929, 2025). "Myeloperoxidase (MPO) is one such marker that has been assessed in patients with depression and has been found to be positively correlated with the severity of depression." (PMID 35203908, 2022). "When the control variables (Model 2) were included in the hierarchical logistic-regression analysis, MPO remained a significant predictor of AMI-induced depression (MPO: p= 0.025)." (PMID 36358455, 2022). "The results of the present study indicate that patients with AMI-induced depression have significantly lower levels of MPO immediately and 6 months after AMI." (PMID 36358455, 2022). "Protein expression of the MPO gene was significantly lower in patients with depression compared to healthy individuals (p = 0.0006)." (PMID 35743392, 2022). "The baseline MPO was observed as a significant predictor (p = 0.027) of AMI-induced depression 6 months after AMI." (PMID 36358455, 2022). "Regarding Model 1, the baseline MPO was a significant predictor of AMI-induced depression (MPO: p = 0.027)." (PMID 36358455, 2022). "Our results contradict these findings, since expression of MPO was significantly lower in our patients with depressive disorders than in the control group, both at the mRNA and protein levels." (PMID 35743392, 2022). "Myeloperoxidase was previously reported as an enzyme of inflammation important in the etiology of recurrent depressive disorders." (PMID 35453861, 2022).
depression (continued). "On the other hand, the expression of the MPO gene at the mRNA level was significantly lower in patients with depressive disorders than in the control group (p = 0.0014)." (PMID 35743392, 2022). "On the other hand, the expression of the MPO gene at both mRNA and protein levels was significantly lower in patients with depressive disorder than in the control group." (PMID 35743392, 2022). "Additionally, MPO is considered a potential biomarker for depression following acute myocardial infarction, linking depressive symptoms to innate immune suppression." (PMID 40401059, 2025). "Additionally, a previous study reported increased MPO activity in mice exhibiting both depression-like and anxiety-like behaviors, suggesting a possible link between MPO and anxiety." (PMID 40401059, 2025). "MPO has also been implicated in PTSD, as well as major depressive disorder (MDD)." (PMID 37333909, 2023). "Additionally, increased levels of myeloperoxidase (MPO), a key enzyme in the innate immune response, has been frequently reported in depression." (PMID 36231075, 2022). "This indicates that different forms of depression might exist, which might be reflected in different MPO levels." (PMID 36358455, 2022). "Taking into account its importance in inflammatory processes and in maintaining oxidative balance, we hypothesized that the expression of the gene for MPO may also play a role in the etiopathogenesis of depression." (PMID 35743392, 2022). "Our findings may not support the utility of paraoxonases (PON) or myeloperoxidase (MPO) as promising biomarker candidates of depression pending larger and well controlled studies." (PMID 35743392, 2022). "Research data on the role of myeloperoxidase (MPO) in depression seems to be much more consistent." (PMID 35743392, 2022). "MPO is considered an important biomarker in major depressive disorder." (PMID 34821692, 2021). "CSS significantly reduced the RS-induced anxiety- and depression-like behaviors and hippocampal NF-κB activation and IL-6 expression, blood corticosterone level, and colonic IL-6 expression and myeloperoxidase activity, while the RS-suppressed BDNF expression increased." (PMID 34391441, 2021). "A connection may exist between depression and both oxidative stress and coagulation in the increased levels of serum myeloperoxidase (MPO) and fibrinogen respectively." (PMID 26231223, 2015). "Previously, we have shown that myeloperoxidase, cyclooxygenase-2 and inducible nitric oxide synthase mRNA expression and protein levels were significantly higher in patients with recurrent depressive disorders than in healthy controls." (PMID 25880127, 2015). "Based on our findings, we doubt whether paraoxonases (PON) or myeloperoxidase (MPO) are promising candidates to be accepted as reliable biomarkers of depression; both their activity and expression depend on many factors and may not only be related to depression." (PMID 35743392, 2022). "For instance, myeloperoxidase (MPO), a marker of innate immune activity, is significantly lower in post-MI patients with depression at baseline and 6 months." (PMID 41301929, 2025). "Inflammatory markers such as manganese superoxide dismutase (MnSOD), myeloperoxidase (MPO), and inducible nitric oxide synthase, along with proinflammatory and anti-inflammatory cytokines, play crucial roles in the pathogenesis of depression." (PMID 39200687, 2024). "MPO-AAV-CFS patients: however, had similar frequencies of anxiety, depression and sleep disturbance diagnoses as FM patients." (PMID 36890852, 2023). "Increased MPO and AOPP have been reported in relation to depression, anxiety, and cognitive impairment." (PMID 36675440, 2023). "Mice were evaluated for behavioral alterations related to depression and memory and oxidative status [brain levels of thiobarbituric acid reactive substances (TBARS), reduced glutathione (GSH), and myeloperoxidase (MPO)]." (PMID 36259798, 2022).
depression (continued). "The FMT from HV suppressed colon shortening, reduced myeloperoxidase activity, and IL-6 expression in the colon of mice with the IBD/D+-F-induced depression." (PMID 34650107, 2021). "By considering the clinical importance of MPO and its clinical relation with IBS and depression, we investigated the serum level of MPO in this study." (PMID 29997457, 2018). "Decreased MPO blood concentrations immediately and 6 months after AMI may reflect a suppression of the innate immune system in depression-vulnerable AMI patients." (PMID 36358455, 2022). "Therefore, while searching for reliable biological markers of depression, we also considered factors influencing the oxidative balance of the organism, such as paraoxonases (PON) and myeloperoxidase (MPO)." (PMID 35743392, 2022). "The patients with AMI-induced depression 6 months after AMI showed significantly lower MPO blood levels compared to AMI patients without depression immediately and 6 months after the AMI." (PMID 36358455, 2022). "The depressive patients showed significantly lower MPO blood levels immediately and 6 months after the AMI compared to the patients without depression (ANCOVA: MPO (depression) F = 4.764, df = 1, p = 0.031)." (PMID 36358455, 2022). "In the first step, we regressed the MPO at the time of hospital admission against AMI-induced depression 6 months after AMI (depression six months after AMI: yes/no) (Model 1)." (PMID 36358455, 2022). "By contrast, the MPO 6 months after the AMI is not a significant predictor of AMI-induced depression 6 months after AMI." (PMID 36358455, 2022). "The dizygotic twins with major depression had significantly higher serum levels of MPO than those without depression." (PMID 36358455, 2022). "In addition, the data in this study demonstrate that baseline MPO concentrations, which were measured immediately after the AMI, were significant predictors of AMI-induced depression in the long term." (PMID 36358455, 2022). "The symptoms of depression do not appear to be correlated with MPO, but both inflammation and depression have common pathophysiological pathways." (PMID 34821692, 2021). "Other inflammatory markers were found in depressive disorder, but their values were not as high as MPO." (PMID 34821692, 2021). "MPO has also been studied in various clinical trials as an inflammatory biomarker and used to diagnose the IBD and pro-oxidative processes in patients with depression." (PMID 29997457, 2018). "Since MPO serves as an indicator of neutrophil function and the function of the innate immune system, the potential suppression of the innate immune system in patients with AMI-induced depression might be evidenced by a decrease in MPO blood levels." (PMID 36358455, 2022). "Shows the levels of MPO in patients with and without AMI-induced depression." (PMID 36358455, 2022).
pneumonia (40 papers, 2013 to 2025). An acute, acute and chronic, or chronic inflammation focally or diffusely affecting the lung parenchyma, caused by an infection in one or both of the lungs (by bacteria, viruses, fungi, or mycoplasma.). "Thus, in the work of the authors Nagoev and Betsucova, it was shown that the more severity of influenza-associated pneumonia, the greater inhibition of MPO activity of neutrophils was." (PMID 33014465, 2020). "In addition, FOM decreased MPO activity, pulmonary vascular permeability and edema formation in the lungs of mice with S. aureus-caused pneumonia." (PMID 31380296, 2019). "Nevertheless, this is the first study to conduct a histological examination in PR3‐ANCA‐positive interstitial pneumonia in comparison with MPO‐ANCA‐positive pneumonia." (PMID 40070290, 2025). "Biochemical assays revealed that mice receiving fecal microbiota transplantation from pneumonia patients exhibited higher myeloperoxidase (MPO) levels after infection with P. aeruginosa." (PMID 40736248, 2025). "Initial management of pneumonia proved ineffective, and further investigation revealed strongly positive myeloperoxidase (MPO)-ANCA antibodies." (PMID 41306180, 2025). "Chest computerized tomography (CT) showed pneumonia and blood tests showed blood creatinine of 835 umol/L (9.4 mg/L), pANCA and myeloperoxidase (MPO) positive." (PMID 36961149, 2023). "The results indicated that JTKY treatment decreased the neutrophil ratio and MPO levels in the lungs of poly(I:C)-induced pneumonia model mice." (PMID 36147321, 2022). "Most importantly, recombinant MPO significantly reduced the morbidity and mortality of murine pneumonia induced by Pseudomonas aeruginosa or methicillin-resistant Staphylococcus aureus." (PMID 35019674, 2022). "MPO-DNA complexes were detected in all BAL samples from influenza pneumonia and VZV pneumonia patients but only in 2 of 6 available paired plasma/serum samples from influenza cases and 1 of 3 paired plasma samples from VZV cases." (PMID 33021967, 2020). "According to other data, weighting the course of pneumonia significantly increases the activity of myeloperoxidase." (PMID 33014465, 2020). "Inflammation and lung leakage, both markers of pneumonia, were examined by assaying myeloperoxidase (MPO) activity, a measure of neutrophil numbers, and albumin level respectively in the bronchoalveolar lavage (BAL) fluid collected from the mice." (PMID 28074841, 2017). "Clinical symptoms of pneumonia and myeloperoxidase activity, as a measure of neutrophil activation in the lung tissue, were assessed." (PMID 25706529, 2015). "In this study, nafithromycin caused inhibition of pro-inflammatory markers such as myeloperoxidase (MPO), TNF-α and IL-6, which may provide additional clinical benefits by resolving the secondary complications associated with severe pneumonia." (PMID 36226226, 2022). "Moreover, the blood level of MPO+ Cit-H3+ NETs in healthy controls was lower than in patients admitted to the ICU for SARS-CoV2 related pneumonia." (PMID 33708778, 2021). "In our opinion, this may be due to the fact that the activity of the enzyme depends on the etiology of the disease, since it has been shown that the development of pneumonia from influenza infection reduces MPO activity." (PMID 33014465, 2020). "Further, this group showed that the MPO deficient mice that received nonviable Candida albicans showed more severe pneumonia with significantly higher numbers of alveolar neutrophils than wild-type mice." (PMID 26998194, 2016). "Interestingly, during secondary pneumonia after primary influenza infection, intense pulmonary NETs generation together with elevated myeloperoxidase activity and cytokine dysregulation determined the disease severity." (PMID 27034012, 2016). "Infectious events in our patient (cellulitis right leg, pneumonia) might have triggered MPO-ANCA titers increase." (PMID 26266064, 2015).